MIIP (migration and invasion inhibitory protein)
Diseases named in the same sentence as MIIP in open-access papers (continued):
Sharing a sentence is not in itself a finding about the gene and the disease.
tumor (continued). "To analyze communication between MIIP-downregulated tumors and adipocytes, we established in vitro and in vivo models and demonstrated that MIIP down-regulated tumor cells enhanced adipocyte browning and lipolysis, as well as the tumor-promoting function of adipocytes by releasing FFAs into the TME." (PMID 38245780, 2024). "Given angiogenesis is a fundamental and crucial event for tumor growth, which has been characterized as one of the hallmarks of cancer and the promising target for cancer therapy, we wondered whether MIIP inhibits growth of TNBC via suppressing tumor angiogenesis." (PMID 36130933, 2022). "Therefore, MIIP is a novel tumor suppressor in RCC and may serve as a potential therapeutic molecule for RCC treatment." (PMID 34931765, 2021). "Consequently, tumor cells expressed with WT MIIP exhibited the strong capability of metastasis." (PMID 29038521, 2017). "Migration and invasion inhibitory protein (MIIP) contains 388 amino acids and is considered to be a novel tumor suppressor that can inhibit RCC proliferation and angiogenesis by negatively regulating." (PMID 41181710, 2025). "As a genetic engineering bacterium, VM exhibits unique and synergistic anti-tumor effects through its bacterial components VNP20009 and anti-cancer protein MIIP." (PMID 38372808, 2024). "To address this, we investigated MIIP protein levels in 14 paired samples of CRC, comparing tumor and adjacent normal tissues." (PMID 38245780, 2024). "MIIP inhibition of miRNA 181a-5p and 181b-5p also leads to reduced expression of SNAIL and TWIST, and knockdown of MIIP promoted tumor growth or osteolytic bone lesions, as well as AR activity." (PMID 33672595, 2021). "To evaluate the clinical relevance of MIIP in RCC, we collected 13 pairs of human RCC specimens together with their corresponding adjacent non-tumor tissues, and detected MIIP levels by Western blot." (PMID 34931765, 2021). "Migration and invasion inhibitory protein (MIIP), also known as invasion inhibitory protein 45 (IIp45), is recently identified as a tumor suppressor." (PMID 31092266, 2019). "Intriguingly, phosphorylated MIIP protects deacetylation of RelA from HDAC6, thereby ensures EGFR-stimulated RelA transcriptional activity and potentiates tumor metastasis." (PMID 29038521, 2017). "Oxaliplatin alone exhibited partial inhibition of tumor growth, irrespective of the MIIP expression level, compared to the vehicle-treated group." (PMID 38245780, 2024). "However, we did not detect any significant changes in CD36 abundance in mice injected with HCT116 (MIIP+/− or WT) alone, suggesting that CD36 upregulation in tumor cells was attributed to adjacent adipose browning." (PMID 38245780, 2024). "In a tumor-bearing mouse model, inhibition of β-adrenergic receptor or FFA uptake, combined with oxaliplatin, significantly improved therapeutic efficacy in CRC with abnormal MIIP expression." (PMID 38245780, 2024). "Moreover, our results also demonstrate that chemotherapy drugs combined with WAT browning or FFAs uptake inhibitors have an impressive synergistic anti-tumor effect, which provides new ideas for the treatment of CRC with abnormal MIIP expression." (PMID 38245780, 2024). "MIIP downregulation promoted N-glycosylation and over-secretion of AZGP1 in tumor cells." (PMID 38245780, 2024). "To this end, we first detect expression of two classic markers for angiogenesis, CD34 and VEGF, in tumor tissues formed from MDA-MB-231 cells with or without MIIP overexpression." (PMID 36130933, 2022). "Moreover, among 8 pairs of samples with reduced MIIP, 7 pairs showed clearly upregulated HIF-2α and CYR61 expression in tumor tissues." (PMID 34931765, 2021). "As a newly identified tumor suppressor, MIIP exerts its role in various types of cancer but has not been investigated in PCa." (PMID 31092266, 2019). "However, either EGF-enhanced tumor cell invasion or EGF-induced transcription of MMP2 and Twist was compromised by MIIP depletion." (PMID 29038521, 2017).
tumor (continued). "Similar with that of HCT116, MIIP S303A expression which blocked promoter-enrichment of MIIP or RelA Ac-K310 in CaCo2 cells, inhibited transcription of MMP2 and Twist and tumor cell invasion." (PMID 29038521, 2017). "Consistent with the increased secretion of FFAs from beige adipocytes in the tumor microenvironment (TME), cells incubated with adipocyte CM pretreated with MIIP+/− cancer cell CM exhibited higher expression levels of FFA transporters, CD36 and FABP4, compared to cells treated with WT (MIIP+/+) CM." (PMID 38245780, 2024). "Although the MIIP expression levels were not correlated with age, gender, tumor size, or TNM stage (P > 0.05), low expression of MIIP was significantly associated with a higher histological grade (P < 0.01) (WHO histological grade) and distant metastasis (P < 0.05)." (PMID 34931765, 2021). "Additionally, Etomoxir (Eto, a CPT1a inhibitor) significantly impaired the OCR (oxygen consumption rate) of parental HCT116 cells incubated with tumor-adipocyte-co-cultured supernatant, particularly in MIIP+/−-derived supernatant cultured cells but not in conventional (McCoy's 5A) cultured cells." (PMID 38245780, 2024).
cancer (13 papers, 2016 to 2026). A tumor composed of atypical neoplastic, often pleomorphic cells that invade other tissues. "MIIP gene is located at chromosome 1p36.22, which is a frequently deleted region in numerous cancers, and encode a cytosolic protein with molecular weight of 45 kDa." (PMID 31092266, 2019). "To assess the significance of CD36 in fatty acid transportation, we generated HCT116 cells with stable CD36 knockdown and subsequently incubated them with adipocyte CM pretreated with MIIP+/− cancer cell CM." (PMID 38245780, 2024). "To investigate further, we treated mature adipocytes with a specific inhibitor of β-adrenergic receptors, SR59230A, in the presence of CM from MIIP+/− or WT cancer cells." (PMID 38245780, 2024). "Since the identification of MIIP, a limited number of studies addressed the function and mechanism of MIIP in tumorigenesis, with most of them indicate MIIP plays inhibitory effects on tumorigenesis in many types of cancer." (PMID 36130933, 2022). "The deletion of 1p.36 locus including MIIP (migration and invasion inhibitory protein) gene results in lower gene expression in EC and in vitro conditions reflect the cancer stage." (PMID 32443784, 2020). "MIIP Ser303 phosphorylation displays an inverse relationship with PP1 protein levels in cancer cells." (PMID 29038521, 2017). "Here, we show that activation of EGFR in human cancer cells results in PKCε-dependent MIIP phosphorylation and its interaction with RelA in the nucleus." (PMID 29038521, 2017). "This investigation also provides a foundation for further research into cancer therapeutics exploring the MIIP protein and its mechanism of action." (PMID 27760566, 2016). "Increasing evidence suggests that MIIP is downregulated in various cancer types." (PMID 38245780, 2024). "Moreover, we conducted experiments where adipocytes were incubated with CM from MIIP+/− or WT cancer cells, and β-adrenergic receptor blockade was achieved using either SR59230A or H89-2HCl." (PMID 38245780, 2024). "Our findings revealed a significant decrease in adiponectin levels (encoded by ADIPOQ), which are known for their inhibitory effects on cancer, while there was a marked increase in leptin levels (encoded by LEP), known for their growth-promoting effects, in MIIP+/− CM-treated adipocytes." (PMID 38245780, 2024). "The expression of MIIP is downregulated in many types of cancer." (PMID 34931765, 2021). "The MIIP-containing chromosome 1p36 region has been shown to be deleted in a wide spectrum of human cancers, including EC, which suggests that MIIP may also be a negative regulator of EC progression." (PMID 27760566, 2016). "This reveals a new mechanism through which MIIP inhibits cancer cell proliferation." (PMID 26824318, 2016). "Our results show that downregulation of EGFR by MIIP suppresses cancer cell growth significantly." (PMID 26824318, 2016). "Our previous work showed that MIIP could inhibit cancer cell migration in several types of cancer cells." (PMID 27760566, 2016). "Therefore, it deserves further investigation as whether MIIP serves as a PP1 regulator or a substrate in different cancer type, and whether there exists a reciprocal regulatory relationship between them." (PMID 31092266, 2019). "Differential expression analysis showed higher expression of MIIP, TTK, and EIF4A in tumors versus normal tissues across various cancers." (PMID 39015573, 2024). "In various cancers, migration and invasion inhibitory protein (MIIP) is expressed at low level and is involved in cancer pathogenesis." (PMID 34931765, 2021). "Importantly, we demonstrated that the combination of chemotherapy drugs with inhibitors of WAT browning or FFAs uptake resulted in improved anti-cancer efficacy, presenting a novel therapeutic approach for treating CRC with abnormal MIIP expression." (PMID 38245780, 2024).
cancer (continued). "Whether MIIP regulates HIF-1α and HIF-2α through these 2 mechanisms simultaneously, differentially, or in a cancer-type dependent manner remains to be investigated." (PMID 34931765, 2021). "We identified two genomically co-localized signatures, UBE2J2 and MIIP located on 1p36.33-36.22 that have not been detected as pan-cancer deleted regions." (PMID 33057153, 2020). "As a migration and invasion inhibitory protein and a metastasis suppressor, MIIP was reported to bind to and antagonize the function of diverse effectors, including IGFBP-2, HDAC6 and PAK1, depending on different molecular context in different cancer types." (PMID 31092266, 2019). "In summary, the identification of MIIP as an inhibitor of Rac1 signaling by competitive binding to its downstream effector protein PAK1 has expanded our understanding of these pathways and shed light on how the cell migration pathways can be activated in cancer." (PMID 27760566, 2016).
adenocarcinoma (3 papers, 2014 to 2024). A common cancer characterized by the presence of malignant glandular cells. "More importantly, MIIP expression was identified as an independent predictor for overall survival of adenocarcinoma NSCLC patients." (PMID 26824318, 2016). "Spearman's correlation analysis demonstrated that the immunoreactivity score of MIIP was significantly inversely correlated with that of EGFR in adenocarcinoma NSCLC specimens." (PMID 26824318, 2016). "We next analyzed the expression of MIIP protein in a cohort of 243 Stage IA-IIIA adenocarcinoma NSCLC patients who underwent radical surgery." (PMID 26824318, 2016). "And higher MIIP protein expression predicts a favorable survival of adenocarcinoma NSCLC patients." (PMID 26824318, 2016). "The positive staining of MIIP could be detected in 99.6% (242/243) adenocarcinoma NSCLC specimens." (PMID 26824318, 2016). "The negative correlation between MIIP and EGFR protein expression observed in vitro was verified in adenocarcinoma NSCLC specimens." (PMID 26824318, 2016). "To verify the in vitro results of negative correlation between MIIP and EGFR protein expression, we evaluated the expression level of MIIP and EGFR protein in 28 pairs of clinical adenocarcinoma NSCLC specimens by immunohistochemistry." (PMID 26824318, 2016).
infection (3 papers, 2016 to 2021). The state of being infected such as from the introduction of a foreign agent such as serum, vaccine, antigenic substance or organism. "Both gain-of-function (infection) and loss-of-function (siRNA) assays were used to alter MIIP expression levels." (PMID 27760566, 2016). "Using both gain-of-function (infection) and loss-of-function (siRNA) assays, we show that MIIP markedly blocked EC cell migration, whereas loss of MIIP led to increase in EC cell migration." (PMID 27760566, 2016). "To investigate the role of MIIP in PCa cells, we established MIIP-overexpressing stable cell lines (LNCaP-MIIP and C4–2-MIIP) by lentivirus infection." (PMID 31092266, 2019). "To determine the role of MIIP in ccRCC cells, we first established MIIP-stably overexpressing OS-RC-2 and 786-O and MIIP-silenced HK-2 and 786-O cell lines through lentivirus infection, on the basis of the endogenous expression of MIIP in HK-2 cells and several ccRCC cell lines." (PMID 34931765, 2021).
MIIP also shares sentences with these, for which no sentence is quoted: clear cell adenocarcinoma (1 paper); esophageal squamous cell carcinoma (1); neuroblastoma (1); oligodendroglioma (1); Stillbirth (1).